Y_RNA (Y RNA )
Gene: Miscellaneous RNA gene on chromosome 1 (62,211,557 to 62,211,666, forward strand). Ensembl gene ENSG00000200174.
Homologues: Orthologues: chimpanzee Y_RNA (100% identical), macaque Y_RNA (85% identical). Paralogues in human: RNY1P2 (89% identical), Y_RNA (82% identical), Y_RNA (80% identical), Y_RNA (78% identical), Y_RNA (77% identical), Y_RNA (76% identical), RNY1 (75% identical), Y_RNA (75% identical), RNY1P5 (75% identical), Y_RNA (74% identical), Y_RNA (73% identical), RNY1P14 (72% identical), and 91 more.